SAP30 (Sin3A associated protein 30)
Description:
Involved in the functional recruitment of the Sin3-histone deacetylase complex (HDAC) to a specific subset of N-CoR corepressor complexes. Capable of transcription repression by N-CoR. Active in deacetylating core histone octamers (when in a complex) but inactive in deacetylating nucleosomal histones. (Microbial infection) Involved in transcriptional repression of HHV-1 genes TK and gC.
Tractability: PROTAC: UniProt records ubiquitination sites on it; ubiquitination databases record sites on it; its protein half-life has been measured.
Gene: Protein-coding gene on chromosome 4 (173,369,969 to 173,377,532, forward strand). Ensembl gene ENSG00000164105.
Subcellular location: Nucleus
Subcellular location (Human Protein Atlas): Nucleoplasm
Pathways (Reactome):
Chromatin organization: HDACs deacetylate histones
Disease: Potential therapeutics for SARS
Gene expression (Transcription): NoRC negatively regulates rRNA expression
Gene Ontology:
Molecular function: protein binding; transcription corepressor activity; transcription coregulator activity
Biological process: negative regulation of transcription by RNA polymerase II; negative regulation of cell migration; negative regulation of stem cell population maintenance; negative regulation of transforming growth factor beta receptor signaling pathway; positive regulation of stem cell population maintenance; regulation of DNA-templated transcription
Cellular component: histone deacetylase complex; nucleoplasm; nucleus; Sin3-type complex
Genetic constraint (gnomAD): Loss-of-function variants: 6 observed, 8.2 expected, observed/expected ratio (o/e) 0.73, 90% interval 0.4 to 1.43. That is too few expected variants to judge how well the gene tolerates losing a copy. Missense variants: 188 observed, 153.94 expected, observed/expected ratio (o/e) 1.22, 90% interval 1.08 to 1.38. Synonymous variants: 76 observed, 60.99 expected, observed/expected ratio (o/e) 1.25, 90% interval 1.03 to 1.51.
Homologues: Orthologues: chimpanzee SAP30 (99% identical), macaque SAP30 (98% identical), dog SAP30 (98% identical), rabbit SAP30 (98% identical), guinea pig SAP30 (97% identical), pig SAP30 (97% identical), mouse Sap30 (96% identical), rat Sap30 (96% identical), tropical clawed frog sap30 (67% identical), Drosophila melanogaster Sap30 (40% identical). Paralogues in human: SAP30L (58% identical).
Diseases named in the same sentence as SAP30 in open-access papers:
SAP30 is named in the same sentence as 23 diseases in open-access papers, as found by Europe PMC text mining. Sharing a sentence is not in itself a finding about the gene and the disease. The quoted sentences say what the papers report.
breast carcinoma (2 papers, 2022 to 2023). "Kaplan-Meier analysis of 5 independent GEO data sets revealed that high levels of SAP30 were associated with poor overall and metastasis-free survival of patients with breast cancer." (PMID 37655663, 2023). "Although the molecular mechanism underlying SAP30 upregulation in breast tumors remains to be determined, our findings reveal that SAP30 is an independent prognostic factor for breast cancer and has a strong clinical relevance in patients with breast cancer." (PMID 37655663, 2023). "Also, PRKCα's high expression (P-value = 0.046) and SAP30 lower expression (P-value < 0.001) were associated with a higher survival rate in breast cancer." (PMID 36476410, 2022). "SAP30 enhanced chromatin accessibility and RNA polymerase II occupancy at promoters in breast cancer cells, acting as a coactivator for genes involved in cell motility, angiogenesis, and lymphangiogenesis, thereby driving tumor progression." (PMID 37655663, 2023). "Again, only SAP30 mRNA exhibited a gradual increase from the lowest level in luminal A breast cancer to the highest level in triple-negative breast cancer (TNBC), which correlated with tumor aggressiveness." (PMID 37655663, 2023). "We further identified similar oncogenic phenotypes for MLL1 in breast cancer, providing functional evidence of the SAP30/SIN3/MLL1 complex as representative of a transcriptional dependency in breast cancer." (PMID 37655663, 2023). "SAP30 recruits MLL1 via its transactivation domain leading to transcriptional coactivation in breast cancer cells." (PMID 37655663, 2023). "Taken together, these results indicate that MLL1 interacts with SAP30/SIN3A and acts as a downstream executor to control the transcription of SAP30/SIN3-coactivated genes in breast cancer cells by increasing H3K4me3 levels." (PMID 37655663, 2023). "In various breast cancer mouse models, we found that SAP30 promoted tumor growth and metastasis through its interaction with SIN3A/3B." (PMID 37655663, 2023). "Our findings suggest that, by hijacking MLL1, SAP30 increases chromatin accessibility and RNA polymerase II recruitment to turn on transcription of its coactivated genes in breast cancer cells." (PMID 37655663, 2023). "We showed here that SAP30 promotes cancer cell motility, angiogenesis, and lymphangiogenesis in mouse breast cancer models, which is consistent with its effect on gene induction." (PMID 37655663, 2023). "In the present study, for the first time to our knowledge, we identified an oncogenic activity of a previously unappreciated SAP30 protein in breast cancer." (PMID 37655663, 2023). "Collectively, our findings reveal that SAP30 represents a transcriptional dependency in breast cancer." (PMID 37655663, 2023). "Homozygous KO of SAP30 modestly but significantly inhibited mammary tumor initiation compared with wild-type (WT) or heterozygous deletion of SAP30." (PMID 37655663, 2023). "SAP30 promotes luminal mammary tumor initiation, growth, and distant metastasis in a genetically modified mouse model." (PMID 37655663, 2023). "Given the identical role of SAP30 in both luminal breast cancer and TNBC, we used TNBC models to investigate the mechanism of SAP30-mediated breast tumor progression." (PMID 37655663, 2023). "At postnatal day 155, we harvested mammary tumors from these mouse models and found that both total tumor number and weight were significantly reduced in SAP30-homozygous-KO mice compared with SAP30-WT or heterozygous mice." (PMID 37655663, 2023). "In conclusion, our work identifies SAP30 as a clinically relevant target in breast cancer." (PMID 37655663, 2023). "Collectively, these findings indicate that SAP30 is upregulated in all major molecular subtypes of breast tumors, particularly metastatic breast tumors, and correlates with poor clinical outcomes in patients with breast cancer." (PMID 37655663, 2023).
breast carcinoma (continued). "However, only SAP30 mRNA was upregulated in all of 3 Gene Expression Omnibus (GEO) data sets with clinically annotated breast cancer." (PMID 37655663, 2023). "To determine the role of SAP30 in luminal breast cancer development, we generated Sap30-KO mice by deleting exons 2 and 3 of the Sap30 gene with the CRISPR/Cas9 technique and crossed these mice with MMTV-PyMT transgenic mice, a well-characterized mouse model of luminal mammary tumor." (PMID 37655663, 2023). "SAP30 promotes breast cancer progression in a SIN3A/3B-dependent manner." (PMID 37655663, 2023). "Distinct to nuclear receptors, the canonical and the noncanonical SIN3 complex coordinates with its respective corepressors HDAC1/2 and coactivator MLL1 to control their unique sets of genes in breast cancer cells, and SAP30 plays a determinant role in this coordination." (PMID 37655663, 2023). "Lastly, we investigated whether MLL1 is required for SAP30-mediated breast cancer progression." (PMID 37655663, 2023). "We next studied whether SAP30 mediates breast cancer progression through the SIN3 complex." (PMID 37655663, 2023). "Together, these results suggest that each subunit of homodimeric SAP30 respectively binds to MLL1 and SIN3A through F186/F200 residues in breast cancer cells." (PMID 37655663, 2023). "This binding model suggests that SAP30 acts as a molecular hub connecting with SIN3A and MLL1 to coordinate gene transcription in breast cancer cells." (PMID 37655663, 2023). "Here, we show that SAP30 was a nonmutational oncoprotein upregulated in more than 50% of human breast tumors and correlated with unfavorable outcomes in patients with breast cancer." (PMID 37655663, 2023). "While several HDAC inhibitors are currently in clinical trials with breast cancer, the SAP30/SIN3 complex may not become a biomarker for guidance of HDAC inhibitor therapy in patients with breast cancer." (PMID 37655663, 2023).
hepatocellular carcinoma (2 papers, 2022 to 2023). A malignant tumor that arises from hepatocytes. "SAP30 is an integral component of the histone deacetylation complex, and its high expression was associated with a poor prognosis in hepatocellular carcinoma patients." (PMID 38149239, 2023). "Among the eight mRNAs in the model, the up-expressions of TKTL1, KDELR3, PFKP, SLC2A1, and PGF in hepatocellular carcinoma were confirmed in previous experimental studies, while the over-expression of SAP30 in HCC was reported in an earlier computational study." (PMID 36362375, 2022). "In addition, the up-expressions of SAP30 and PPFIA4 were also, respectively, verified in a bioinformatics study of hepatocellular carcinoma and an experimental study of colorectal carcinoma." (PMID 36362375, 2022). "We obtained a prognostic signature including eight hypoxia genes (ENO2, KDELR3, PFKP, SLC2A1, PGF, PPFIA4, SAP30, and TKTL1) and further established a hypoxia-related prognostic ceRNA network including 17 lncRNAs, six miRNAs, and seven mRNAs for hepatocellular carcinoma." (PMID 36362375, 2022).
leukemia (2 papers, 2022 to 2023). A malignant (clonal) hematologic disorder, involving hematopoietic stem cells and characterized by the presence of primitive or atypical myeloid or lymphoid cells in the bone marrow and the blood. "In this study, we showed that deletion of UHRF1 significantly prolongs the survival time of the mice with AML by targeting the self-renewal of leukemia initiating cells through SAP30-mediated MXD4 activation." (PMID 36302855, 2022).
abortion (1 paper, 2008). the ending of pregnancy by removing a fetus or embryo before it can survive outside the uterus. "Theoretically, all the genes whose promoters interact with SAP30 and/or YY1 could be a target for NSs/SAP30-dependent abnormal transcriptional regulation, possibly explaining some of the pathogenic effects due the virus such as abortion, hemorrhagic fever, hepatitis or encephalitis." (PMID 18225953, 2008).
basal cell carcinoma (1 paper, 2006). A carcinoma involving the basal cells. "In addition, loss of heterozygosity of the region 4q32 in the long arm of chromosome 4, which includes ING2 and SAP30, was found in 20% of basal cell carcinomas, suggesting that genetic alteration of the ING2 gene does occur in human tumours." (PMID 16755297, 2006).
breast tumors (1 paper, 2023). "Collectively, these findings indicate that SIN3A and SIN3B phenocopy SAP30 to promote breast tumor angiogenesis, growth, and metastasis in vitro and in vivo." (PMID 37655663, 2023). "Taken together, these results indicate that SAP30 promotes luminal breast tumor initiation and progression in a genetically modified mouse model." (PMID 37655663, 2023). "Collectively, these findings indicate that SAP30 promotes breast tumor growth, tumor angiogenesis, lymphangiogenesis, and distant metastasis in a SIN3A/3B-dependent manner." (PMID 37655663, 2023). "Next, we performed immunohistochemical staining to assess SAP30 protein levels in human breast tumors." (PMID 37655663, 2023). "The extent to which these primary and metastatic breast tumors acquire the transcriptional dependency on the SAP30/SIN3/MLL1 complex remains uncertain." (PMID 37655663, 2023). "SAP30 is upregulated in human breast tumors and correlates with poor survival of patients." (PMID 37655663, 2023). "MLL1 is required for SAP30-mediated breast tumor growth and metastasis." (PMID 37655663, 2023). "Notably, SAP30 protein was significantly elevated in metastatic breast tumors compared with the matched primary tumors." (PMID 37655663, 2023). "In this study, we demonstrated that SAP30 was upregulated in human breast tumors." (PMID 37655663, 2023). "SAP30 KO1 or KO2 significantly inhibited breast tumor growth in mice compared with SC." (PMID 37655663, 2023). "MLL1 was required for SAP30-mediated transcriptional coactivation and breast tumor progression." (PMID 37655663, 2023). "Instead, breast tumors with high levels of SAP30 are most likely vulnerable to MLL1 inhibitor." (PMID 37655663, 2023). "In line with human breast tumors, MMTV-PyMT tumors strongly expressed SAP30 protein compared with normal mammary glands." (PMID 37655663, 2023). "SAP30 hijacks a prominent epigenetic regulator, MLL1, to enhance cancer cell motility, angiogenesis, and lymphangiogenesis, leading to breast tumor progression." (PMID 37655663, 2023). "We further found that mRNAs of SAP30, HDAC1, RBBP4, and RBBP7 but not other core subunits were significantly induced in all 4 major subtypes of breast tumors." (PMID 37655663, 2023). "Rather than being a corepressor, SAP30 coordinates with SIN3A/3B and MLL1 to increase chromatin accessibility and coactivate the transcription of genes involved in cell motility, angiogenesis, and lymphangiogenesis, leading to breast tumor growth and metastasis to distant organs." (PMID 37655663, 2023).
ischemic stroke (1 paper, 2023). A stroke disorder caused by obstruction of blood flow to the brain, due to thrombotic (local blood clot formation) or embolic (due to a blood clot or other material traveling from another site) event. "There are few reports on SAP30 in ischemic stroke, while HDAC1 has been reported to play a vital role in neurological diseases." (PMID 37386280, 2023).
kidney cancer (1 paper, 2021). Primary or metastatic malignant neoplasm involving the kidney. "Studies with SAP30 gene have shown its relationship with histone deacetylase process in eukaryotes that induces Sin3, the histone deacetylases HDAC1 and HDAC2, and acting as a transcription factor for NETO2 gene in kidney cancer." (PMID 34646299, 2021).
liver cancer (1 paper, 2022). An epithelial or non-epithelial malignant neoplasm that arises from the liver. "There are limited studies on the relationship between SAP30 and liver cancer." (PMID 36531219, 2022).
schizophrenia (1 paper, 2022). A major psychotic disorder characterized by abnormalities in the perception or expression of reality. "PHF8, SAP30 and KDM5B as co regulators of the three hub genes may provide a new idea for the treatment of schizophrenia." (PMID 36421842, 2022).
Sepsis (1 paper, 2018). Sepsis is defined as life-threatening organ dysfunction caused by a dysregulated host response to infection. "Gene ontology of these 23 common DEGs showed that apoptotic process (TRAF1, TNFRSF9, ADORA2A, ZBTB16), negative regulation of transcription (SAP30, TSC22D3, ETS2, ZBTB16), and inflammatory response (TNFRSF9, CCL3, ADORA2A) are the main biological processes affected by sepsis treatment." (PMID 30086151, 2018).
viral infection (1 paper, 2025). "For example, the NSs protein of RVFV interacts with SAP30, silencing interferon gene transcription and promoting viral infection." (PMID 40275313, 2025). "Previous studies have shown that SAP30 influences viral infections, it interacts with PBF to recruit the Sin3/HDAC complex, thereby inhibiting HPV transcription, and cooperatively suppresses the transcription of HSV-1-related genes by interacting with HTRP." (PMID 40275313, 2025).
cancer (5 papers, 2018 to 2023). A tumor composed of atypical neoplastic, often pleomorphic cells that invade other tissues. "The high expression of SAP30 was associated with reduced drug sensitivity of cancer cells to one drug (Erlotinib) and with increased drug sensitivity of cancer cells to five drugs (Ifosfamide, Nelarabine, Carmustine, Lomustine, and Arsenic trioxide)." (PMID 36362375, 2022). "SAP30 protein was predominantly localized in the nucleus of cancer cells and upregulated in human ER+, HER2+, and TNBC tumors compared with their adjacent normal tissues." (PMID 37655663, 2023). "Although SAP30 has been implicated to be essential for the SIN3 complex, its precise role in SIN3 complex, gene regulation, and cancer progression remains poorly understood." (PMID 37655663, 2023). "The TCGA data set demonstrates SAP30 upregulation in multiple human cancers." (PMID 37655663, 2023). "Therefore, our findings implicate a broad translational impact of SAP30 in human cancers." (PMID 37655663, 2023). "SAP30 is a core subunit of the transcriptional corepressor SIN3 complex, but little is known about its role in gene regulation and human cancer." (PMID 37655663, 2023). "Furthermore, we identified key transcription factor regulatory networks regulated by HMGB3, SAP30, and E2F8, which likely played crucial roles in the functional characterization of the cancer stem cell-like B cell subpopulation." (PMID 38149239, 2023). "Transcription factor (TF) motifs, including CEBPB (+), FOSB (+), SAP30 (+) and ATF4 (+), were significantly upregulated in CNV high cancer cells, while IRF3 (+), ETV7 (+), STAT1 (+) and IRF7 (+) were downregulated, indicating promising new regulatory networks driven by TFs in OS cells." (PMID 36596773, 2023). "Additionally, we identified the key transcription factor regulatory networks regulated by HMGB3, SAP30, and E2F8 that may play important roles in the functional characterization of the cancer stem cell-like B cell subgroup." (PMID 38149239, 2023).
infection (5 papers, 2008 to 2025). The state of being infected such as from the introduction of a foreign agent such as serum, vaccine, antigenic substance or organism. "SAP30 colocalizes with RVFV NSs filament as early as 5 hours after infection and RVFV NSs interacts with YY1 of the IFN-β gene promoter as soon as 4 hours following infection." (PMID 21994750, 2011). "The interaction of SAP30 with the IFN-β promoter was disrupted after C13 infection when the promoter was activated." (PMID 18225953, 2008). "At these early times after infection, NSs colocalized perfectly with SAP30 whereas colocalization with YY1 appeared only partial." (PMID 18225953, 2008). "In contrast, an important change in the subnuclear distribution of SAP30 was observed at 18 h after ZH infection so that SAP30 appeared predominantly colocalizing with the NSs filament with almost all of SAP30 included into the NSs filament." (PMID 18225953, 2008). "The subnuclear distribution of Sin3A observed in non-infected (a, c) and C13-infected (d, f) cells was affected after ZH-infection (g, i), Sin3A colocalizing with the NSs filament in a way similar to what we have previously observed in the case of SAP30." (PMID 18225953, 2008). "SAP30 can also be “hijacked” by viruses to enhance infection." (PMID 40275313, 2025). "Therefore, RVFV NSs inhibits IFN-β early after infection by interacting with SAP30 then blocks IFN production later during infection by a generalized host cell transcriptional shutoff." (PMID 21994750, 2011). "In RVFV-infected cells, the NSs establishes general transcriptional suppression at a later stage of infection (after 8 h.p.i.), while NSs also suppresses specific IFN-β mRNA transcription at early stages of infection (about 3 h.p.i.)by maintaining repressor complex including SAP30 on IFN-β promoter." (PMID 19197350, 2009). "Furthermore, the RVFV NSs binds to Sin3A-Associated Protein 30 (SAP30), which is important for maintaining the repressor complex containing histone deacetylase 3 on the interferon (IFN)-β promoter, and suppresses the IFN-β promoter activation early in infection." (PMID 19197350, 2009). "It should be noted that although C13 NSs interacts with SAP30 in yeast because it is stabilized as a fusion protein, it is non functional in C13 infected cells since it is degraded by the proteasome, allowing to use C13 infections as negative controls." (PMID 18225953, 2008).